YBX1 (Y-box binding protein 1)
Diseases named in the same sentence as YBX1 in open-access papers (continued):
Sharing a sentence is not in itself a finding about the gene and the disease.
T-cell acute lymphoblastic leukemia (1 paper, 2023). Acute lymphoblastic leukemia of T-cell origin. "Indeed, recent studies have shown that YBX1 may have a critical role in leukemogenesis in non-infectious T-cell acute lymphoblastic leukemia (T-ALL) by regulating expression of the PI3K/AKT and ERK signaling pathways." (PMID 37685922, 2023).
thoracic cancer (1 paper, 2019). A primary or metastatic malignant neoplasm affecting the tissues of the thorax. "We and others have shown that miRNA or siRNA can be used to target YBX1 in thoracic cancer cells in preclinical studies." (PMID 31632972, 2019). "The inhibition of YBX1 by several miRNAs has been shown in other cancers, although to our knowledge such interactions have not been investigated in thoracic cancers." (PMID 31632972, 2019).
Wilms tumor (1 paper, 2023). An embryonal neoplasm characterized by the presence of epithelial, mesenchymal, and blastema components. "We found that core genes (CCT4, HSP90AA1, NCL, PABPC1, YBX1) were lowly expressed in tumor tissue samples and highly expressed in standard tissue samples, which may have reverse regulatory significance for Wilms tumor." (PMID 37058032, 2023).
cancer (418 papers, 2006 to 2026). A tumor composed of atypical neoplastic, often pleomorphic cells that invade other tissues. "YBX1 is an oncogenic transcription factor that is overexpressed in many cancer cells, including RCC, and is associated with tumor growth, angiogenesis and metastasis." (PMID 41507134, 2026). "Lastly, GAS5 displays unique RNA–protein interactions in viral pathogenesis, such as acting as a decoy for viral NS3 or regulating YBX1 in HBV-associated cancers." (PMID 39941145, 2025). "YBX1 is a well-known oncogene that has been implicated in various types of cancers because it affects a wide range of genes involved in cell proliferation, survival, drug resistance and chromatin destabilization." (PMID 41560755, 2025). "As the most prominent member of the YBX family, YBX1 is associated with multiple cancer-related processes." (PMID 40593465, 2025). "Higher NSUN2 expression is linked to more advanced cancer stages and heightened drug resistance, while elevated YBX1 expression correlates with poorer patient survival." (PMID 40114967, 2025). "This class of tRFs has a motif corresponding to Y-box binding protein 1 (YBX1), which is implicated in cancer progression and has been shown to promote cancer metastasis." (PMID 40565284, 2025). "YBX1 is upregulated in numerous malignant tumors and is closely associated with tumor progression and poor prognosis, making it a recognized target for cancer therapy." (PMID 40799245, 2025). "Although YBX1 has also been implicated in mRNA splicing, particularly in cancer models where phosphorylated YBX1 alters ERK signaling via splicing regulation, our results exclude a splicing role in this context." (PMID 41000393, 2025). "We divided the clinical database into two groups based on the expression levels of ALYREF and YBX1 to explore their association with the prognosis of pan cancers." (PMID 38238581, 2024). "The aberrant expression of YBX1 is associated with various diseases, including cancer, inflammatory conditions, and neurodegenerative disorders." (PMID 39727969, 2024). "It appears that future research should actively explore the role of YBX1 in neurogenesis and its relevance to various neural receptor molecules associated with cancer." (PMID 38255791, 2024). "In cancer, specifically, YBX1 expression is closely linked to the progression of multiple malignancies." (PMID 39727969, 2024). "The analysis revealed that YBX1 was found to be a potential risk factor for various types of cancer, such as ACC, LGG, LIHC, and MESO." (PMID 38698857, 2024). "In summary, these results provide supportive evidence that ALYREF and YBX1 are linked to the immunosuppressive microenvironment in cancers." (PMID 38238581, 2024). "ALYREF and YBX1 are both implicated in numerous RNA processing events, and their abnormal expression has been linked to reduced survival rates in cancer patients." (PMID 38238581, 2024). "Our analysis identifies that high YBX1 expression is associated with poor survival in 6 cancer types." (PMID 38538658, 2024). "This novel finding aligns with the established literature that has consistently implicated YBX1 in the upregulation of the MAPK pathway across a range of human cancers." (PMID 38987564, 2024). "The Y-box binding protein-1 (YBX1) gene codes for a multifunctional oncoprotein that is increasingly being linked to the regulations of many aspects of cancer cell biology." (PMID 38538658, 2024). "Our findings demonstrated that ALYREF and YBX1, as m5C readers, are aberrantly expressed in most cancers and are associated with disease prognosis." (PMID 38238581, 2024). "High YBX1 expression was significantly associated with poor survival in 2 female-only and 4 mixed-sex cancer sites." (PMID 38538658, 2024). "YBX1 functions as both a DNA and RNA binding protein and its aberrant expression is associated with cancer proliferation and invasion in numerous tumor tissues." (PMID 36717549, 2023).
cancer (continued). "YBX1 is highly expressed in a variety of malignancies including GBM; in various types of cancer, YBX1 overexpression has been associated with tumor cell proliferation, invasion, apoptotic resistance, drug resistance, and poor prognosis." (PMID 36805592, 2023). "YBX1 is one of the most overexpressed oncogenes observed in human cancer and is highly heterogeneous with several variants and post-translational modifications." (PMID 36936386, 2023). "In contrast, YBX1 acts as a safeguard against the proliferation-to-invasion switch in mesenchymal-like epithelial cancer cells, and its loss accentuates partial-EMT and in vivo invasion." (PMID 36949044, 2023). "The Y-box-binding protein-1 (Ybx1) is a member of Y-box protein family binding DNA and RNA, activating a number of genes associated with cell proliferation and cancer development." (PMID 37059588, 2023). "Y-box binding protein-1 (YB1) is the highly expressed DNA/RNA-binding protein with cold shock domain, and enhanced YB1 expression was proved to be associated with many kinds of malignant tumors." (PMID 35260638, 2022). "YBX1 is a well-known multifunctional oncoprotein that has been implicated in various types of cancers." (PMID 35387975, 2022). "Overexpression of YBX1 is associated with tumorigenic phenotypes and has been shown to facilitate cancer metastasis." (PMID 35186731, 2022). "The acquired TIC-like phenotypes of cancer cells were associated with the activation of ITGB1/YBX1/SPP1/NF-κB signaling." (PMID 34758833, 2021). "The trafficking of YBX1 between the nucleus and the cytosol is closely linked to the transcription of YBX1 target genes in cancer cells." (PMID 34266873, 2021). "Epithelial‐to‐mesenchymal transition (EMT) and transcription/translation regulatory Y‐box binding protein‐1 (YB‐1) have imperative role in association with cancer metastasis." (PMID 33473265, 2021). "Abnormal expression of the transcription factor Y-box-binding protein-1 (YBX1) is associated with the proliferation, migration, aggressiveness, and stem-like properties of various cancers." (PMID 34976785, 2021). "Due to its involvement in these important functions, it is unsurprising that dysregulation of YBX1 is frequently linked to diseases such as cancer." (PMID 32985589, 2020). "Accumulating evidence has shown that aberrant YBX1 expression is closely associated with tumor progression, drug resistance, metastasis and poor prognosis in cancers." (PMID 32760725, 2020). "In many cancers, YBX1 overexpression has been associated with poor prognosis and tumor cell proliferation." (PMID 31481087, 2019). "Although mutations of YBX1 are rare [∼1% in all cancers types], overexpression of YB-1 is found in a wide range of cancers and is often associated with poor prognosis, including NSCLC and MPM." (PMID 31632972, 2019). "YBX1 has been associated with tumorigenesis, tumor progression and resistance to chemotherapy in many cancers." (PMID 31481087, 2019). "In this study, using zebrafish as a vertebrate model system, we show that the nuclear localization of the Y-box binding protein 1 (YB-1), a regulator of cyclin expression and a hallmark of certain cancers, is robustly regulated by the circadian clock." (PMID 28008157, 2017). "The Y-box-binding protein 1 (YBX1) is a well-known oncoprotein implicated in multiple malignant phenotypes of cancers." (PMID 29029484, 2017). "YBX1 expression has been associated with tumor progression and prognosis in multiple types of cancer." (PMID 26779809, 2016). "The transcription/translation regulatory Y-box binding protein-1 (YB-1) is known to be associated with cancer metastasis." (PMID 24770864, 2014). "High YBX1 expression and/or nuclear localization are closely associated with poor prognosis in several types of cancer." (PMID 21170361, 2010).
cancer (continued). "Elevated YBX1 expression has been associated with aggressive disease across multiple cancer types; however, its pan-cancer genomic and clinical correlates, and the extent to which these reflect proliferative activity versus genomic instability, remain incompletely defined." (PMID 42196325, 2026). "Loss of YBX1 expression significantly impedes cell proliferation in various cancer cells." (PMID 40812419, 2025). "YBX1 is associated with the promotion of the expression of genes related to cancer stem cells." (PMID 38255791, 2024). "YBX1 is a multifunctional protein involved in a variety of cellular functions, and its aberrant expression is closely linked to numerous diseases, including cancer, immune disorders, and aging-related conditions." (PMID 39727969, 2024). "Notably, aberrant expression or dysregulation of YBX1 has been closely linked to several pathological conditions, particularly cancer, where it is associated with tumor progression, metastasis, and resistance to therapy." (PMID 39727969, 2024). "YBX1, a multifunctional oncoprotein with both DNA- and RNA-binding capacity, has been reported to promote the proliferation and malignant phenotype of various cancer types and its overexpression often associates with poor prognosis of cancers, including OS29." (PMID 38561347, 2024). "Aberrant expression of YBX1 is associated with uncontrolled cellular proliferation of cancer." (PMID 35861369, 2023). "YBX-1 has been shown to cause treatment failure and cancer progression in EOC." (PMID 35273154, 2022). "However, mutations of the YBX1 gene seem to be rather rarely the case and can be found in only around 1% of all cancer types." (PMID 36330329, 2022). "Recently, accumulating reports on the oncogenic function of YBX1 in cancer biology have predominantly associated its transcriptional role of regulating genes with DNA repair, cell adhesion, angiogenesis, and drug resistance, thus confirming its therapeutic potential." (PMID 34440660, 2021). "More specifically, studies have shown that some tRFs may play a role in cancer suppression by combining with the mRNA binding protein YBX1, which is overexpressed in many cancer types and has been implicated in many key cellular pathways." (PMID 33332661, 2021). "Given the fact that PRMT5, YBX1 and NF-κB are all among top crucial factors in cancer progression, pharmacological disruption of this pivotal axis could serve as the basis for new therapeutics for CRC and other PRMT5/YBX1/NF-κB-associated cancers." (PMID 32985589, 2020). "Elevated levels of nuclear Y-box binding protein 1 (YB-1) are linked to poor prognosis in cancer." (PMID 32013098, 2020). "YBX1 has also been linked to the expression of other cancer-related genes (e.g., c-MYC, CCND1)." (PMID 31461477, 2019). "Y-box binding protein-1, encoded by the YBX1 gene, is a multifunctional oncoprotein involved in many hallmarks of cancer development including driving proliferation, invasion and metastasis, CSC biology, resistance to chemotherapy, hypoxic response, DNA repair and exosomal sorting." (PMID 31632972, 2019). "Therefore, clarifying the precise mechanisms underlying the significant effect of YBX1 on prognosis will aid in the development of therapies for such cancers." (PMID 30647855, 2018). "Targeted disruption of YBX1 alleles resulted in major defects in the G2/M phase, suppression of cell proliferation in cancer cells, associated with a reduction of cells in S-phase of the cell cycle, multi-organ hypoplasia and senescence in response to cellular stress." (PMID 21170361, 2010). "YBX1 exerts its transcriptional regulatory effects by binding to Y-box sequences located in the enhancer and promoter regions of numerous genes, thereby controlling the expression of genes implicated in cancer onset, progression, metastasis, and resistance to therapy." (PMID 41507134, 2026).
cancer (continued). "High YBX1 mRNA expression was associated with increased mutation burden, chromosomal alteration burden, hypoxia, and homologous recombination deficiency at the pan-cancer level, with similar molecular associations observed in tumours stratified by elevated YB-1 protein levels." (PMID 42196325, 2026). "The YBX1 protein is associated with cancer proliferation in numerous tissues, and its gene may be a prognostic marker for poor outcome and drug resistance in certain cancers." (PMID 34476221, 2021). "Here, we performed an integrative pan-cancer analysis across 53 independent datasets spanning 33 tumour types, incorporating transcriptomic (YBX1 mRNA), proteomic (RPPA), genomic, and clinical data." (PMID 42196325, 2026). "YBX1 is highly expressed in various cancers, including breast cancer, liver cancer, pancreatic cancer, and ovarian cancer." (PMID 41507134, 2026). "In cancer, increased expression of YBX1 or increased nuclear distribution ratio was shown to lead to the expression of genes for cell proliferation, differentiation, multi-drug resistance, etc." (PMID 41507135, 2026). "Considering the role of NF-κB in promoting tumors and regulating energy metabolism in cancer, we further demonstrated the function of YBX1 in glycolysis and RCC progression mediated by LDHA through lactic acid production and CCK-8 proliferation assays." (PMID 41507134, 2026). "Previous studies have reported that YBX1 and G3BP1 are associated with tumorigenesis, tumor progression, and resistance to chemotherapy in various types of cancer." (PMID 41513625, 2026). "To investigate the role of YBX1 in ccRCC, we analyzed the expression of YBX1 across various cancers using the UALCAN database." (PMID 41507134, 2026). "The Y-box binding protein-1 (YBX1), a transcription factor implicated in drug resistance across multiple cancers, is highly expressed in HCC and represents a potential therapeutic target." (PMID 41898194, 2026). "YBX1 is a multifunctional hub in cancer and promotes cancer progression through multiple mechanisms in different cancers." (PMID 41507135, 2026). "Y-box binding protein 1 (YB-1) contributed to various cancer malignant phenotypes, including DNA repair, cell proliferation and differentiation, and migration." (PMID 40242036, 2025). "To explore the role of YBX1-dependent PDHA1 activation in cancer cells, we first examined the effect of pyruvate catabolism on cell growth using PDK inhibitors." (PMID 40812419, 2025). "Emerging evidence has established YBX1 as a multifunctional oncoprotein contributing to tumorigenesis across multiple cancer types." (PMID 40783393, 2025). "In summary, targeting YBX1 in cancer therapy offers multiple advantages, including multidimensional inhibition of tumor progression, remodeling of the immune microenvironment, and reversal of drug resistance." (PMID 41346602, 2025). "Mechanistically, MNX1 exists in the cytoplasm of cancer cells and interacts with Y‐box binding protein 1 (YBX1), a multifunctional DNA/RNA‐binding protein, to enhance the binding of YBX1 to PD‐L1 mRNA." (PMID 39912421, 2025). "In the context of cancer, YBX1 promotes tumor growth and metastasis by upregulating oncogene expression, and its overexpression is frequently linked to poor prognosis." (PMID 40114967, 2025). "YBX1 has also been investigated as a therapeutic target in aggressive cancers, although being a DNA/RNA-binding protein makes it challenging to target directly." (PMID 41301491, 2025). "YBX1 is a well-known oncogene, which plays a critical role in the regulation of gene expression involved in cancer progression." (PMID 40812419, 2025). "By focusing on key molecules such as CD2BP2‐DT and YBX1, we broaden the horizons of cancer treatment while highlighting the groundbreaking application of LLPS technology in addressing previously undruggable proteins." (PMID 39976088, 2025).